ZFR (zinc finger RNA binding protein)
Description:
Involved in postimplantation and gastrulation stages of development. Involved in the nucleocytoplasmic shuttling of STAU2. Binds to DNA and RNA (By similarity).
Synonyms: ZFR1; SPG71
Tractability: PROTAC: UniProt records ubiquitination sites on it; ubiquitination databases record sites on it; its protein half-life has been measured.
Gene: Protein-coding gene on chromosome 5 (32,354,350 to 32,444,761, reverse strand). Ensembl gene ENSG00000056097.
Subcellular location: Nucleus; Cytoplasm; Cytoplasmic granule; Chromosome
Subcellular location (Human Protein Atlas): Nucleoplasm
Gene Ontology:
Molecular function: protein binding; RNA binding; double-stranded RNA binding; single-stranded RNA binding; nucleic acid binding; zinc ion binding
Cellular component: chromosome; cytoplasm; nucleus
Genetic constraint (gnomAD): Loss-of-function variants: 19 observed, 127.04 expected, observed/expected ratio (o/e) 0.15, 90% interval 0.1 to 0.22. The upper end of that interval is the gene's LOEUF score, 0.22, which puts it in group 1 of 6, group 1 being the genes least tolerant of losing a copy. Missense variants: 866 observed, 1,350.1 expected, observed/expected ratio (o/e) 0.64, 90% interval 0.61 to 0.68. Synonymous variants: 466 observed, 467.55 expected, observed/expected ratio (o/e) 1, 90% interval 0.92 to 1.08.
Homologues: Orthologues: chimpanzee ZFR (99% identical), dog ZFR (99% identical), rabbit ZFR (99% identical), pig ZFR (99% identical), rat Zfr (98% identical), mouse Zfr (98% identical), macaque ZFR (94% identical), guinea pig ZFR (89% identical), tropical clawed frog zfr (86% identical), zebrafish zfr (80% identical), Drosophila melanogaster Zn72D (38% identical), Caenorhabditis elegans zfr-1 (25% identical), and 3 more. Paralogues in human: ZFR2 (43% identical), ILF3 (18% identical), STRBP (18% identical), ADAR (10% identical), ILF2 (9% identical), ADARB2 (8% identical), ADARB1 (7% identical), ADAD1 (6% identical), ADAD2 (5% identical), ADAT1 (4% identical), STAU2 (4% identical), TARBP2 (4% identical), and 2 more.
Diseases named in the same sentence as ZFR in open-access papers:
ZFR is named in the same sentence as 21 diseases in open-access papers, as found by Europe PMC text mining. Sharing a sentence is not in itself a finding about the gene and the disease. The quoted sentences say what the papers report.
hepatocellular carcinoma (3 papers, 2020 to 2022). A malignant tumor that arises from hepatocytes. "CircRNA_103809 locates at chr5:32379220-32388780 (CircBase ID: hsa_circ_0072088), and was found derived from the ZFR gene and may be associated with tumor relapse of hepatocellular carcinoma." (PMID 32065779, 2020). "In colorectal cancer (CRC) and hepatocellular carcinoma (HCC), FAM49B, as a downstream target of the Zinc Finger RNA binding protein (ZFR), may be a potential tumor suppressor." (PMID 36499755, 2022).
pancreatic cancer (3 papers, 2016 to 2020). "ZFR mRNA levels in human pancreatic cancer tissues were investigated using two datasets from the publicly available oncomine database." (PMID 27177590, 2016). "ZFR has been reported to play an important role in DNA binding and plays an essential role in cell growth and maybe a potent therapeutic target in human pancreatic cancer." (PMID 32536039, 2020). "In this study, we provide new evidence demonstrating that ZFR may be a potential tumor marker in human pancreatic cancer." (PMID 27177590, 2016). "Taken together, these results suggest knockdown of ZFR could inhibit pancreatic cancer cell proliferation might via inducing G0/G1 cell cycle arrest." (PMID 27177590, 2016). "Herein, to investigate whether ZFR is involved in tumor growth, Oncomine microarray data was firstly used to evaluate ZFR gene expression in human pancreatic tumors." (PMID 27177590, 2016). "ZFR (zinc finger RNA‐binding protein) is involved in the regulation of alternative pre‐mRNA splicing and plays an essential role in cell growth and maybe a potent therapeutic target in human pancreatic cancer." (PMID 32536039, 2020). "Our findings provide new evidence that ZFR plays an essential role in cell growth and may be a potent therapeutic target in human pancreatic cancer, based on which we could develop more effective diagnosis approaches for pancreatic cancer to prong the patients survival." (PMID 27177590, 2016). "However, little is known about ZFR function in pancreatic cancer." (PMID 27177590, 2016). "Therefore, it is likely that ZFR could modulate pancreatic cancer growth via the regulation of a subset of cancer-related genes involved in cellular growth and apoptosis." (PMID 27177590, 2016).
breast carcinoma (2 papers, 2016 to 2023). "A previous study revealed that ZFR was a PI3K pathway independent survival gene in breast cancer." (PMID 37461053, 2023).
liver cancer (2 papers, 2024). An epithelial or non-epithelial malignant neoplasm that arises from the liver. "CYRI-B was also highlighted as a target of the zinc finger RNA-binding protein Zfrbp, leading to accelerated tumour development when overexpressed in colorectal and liver cancers." (PMID 38712822, 2024). "Interestingly, other works have reported that ZFR may act as an oncogene in non-small-cell lung, colorectal and liver cancers by inducing tumor progression and metastatization." (PMID 38472212, 2024).
ovarian tumor (2 papers, 2020 to 2022). "In the library prepared from ovarian tumor tissue, 5 clones with coding sequences were identified using the HMGB1 bait (C1QA, DAG1, RPL29, RSF1, TGM2), and 6 (COMMD1, MIEN1, PCBP1, TBC1D25, ZFR, ZNF428) were identified with the HMGB2 bait." (PMID 32867128, 2020).
asthma (1 paper, 2013). "Of the top two regions, KCNIP4 and PDZD2/GOLPH3/MTMR12/ZFR, only KCNIP4 had gene-level replication in the SHARP AHR GWAS at a nominally significant level in the same regions as the asthma GWAS studies." (PMID 23457522, 2013).
bladder cancer (1 paper, 2022). "Circ-zinc finger RNA-binding protein (ZFR), a newly identified circRNA, has been testified to be elevated in bladder cancer (BC) and boost BC cell advancement via augmenting WNT5A signal to absorb miR-545 and miR-1270." (PMID 35543376, 2022).
melanoma (1 paper, 2024). A malignant, usually aggressive tumor composed of atypical, neoplastic melanocytes. "Of importance, we also observed that MITF and ZFR are both down-regulated in two independent datasets of bulk RNA-seq data from melanoma biopsies sequenced before (Pre) or after development of resistance (PD or PROG) to targeted therapies." (PMID 38472212, 2024). "Finally, given that miR-579 is hosted into ZFR gene and is co-transcribed with this gene, the consequent question regards the potential molecular functions of ZFR in melanoma progression and therapy resistance." (PMID 38472212, 2024). "Luciferase results demonstrated that MITF silencing reduces the activation levels of miR-579/ZFR promoter as compared to SCR in LOX IMVI and WM266 melanoma cells." (PMID 38472212, 2024).
myopia (1 paper, 2010). "Six candidate genes CDH6, CDH10, CDH12, PDZD2, GOLPH3, and ZFR at this high myopia locus were selected on the basis of their function to screen for gene mutations by re-sequencing." (PMID 21042559, 2010).
viral infection (1 paper, 2018). "Thus, we have identified ZFR as a strong inhibitor of type I interferon induction and the cellular response to viral infection." (PMID 29559679, 2018).
tumor (10 papers, 2016 to 2025). "In a recent study, it was demonstrated that ZFR is involved in NSCLC tumor growth and metastasis." (PMID 32536039, 2020). "Moreover, circZFR levels were positively correlated with TNM stage of BCa and tumor grades of BCa, which further supports the promotive role of circ-ZFR in tumor development." (PMID 33928018, 2020). "This could be the major triggers for circ-ZFR upregulation in tumor cells." (PMID 33928018, 2020).
cancer (6 papers, 2016 to 2022). A tumor composed of atypical neoplastic, often pleomorphic cells that invade other tissues. "Circular RNA zinc finger RNA-binding protein (CircZFR), a transcription product of zinc finger RNA-binding protein (ZFR) gene, is mapped to chromosome 5p13.3, and has been identified as a novel oncogenic or suppressing modulator in several human cancers." (PMID 36008845, 2022). "Emerging studies have demonstrated that circular RNA (circRNA) zinc finger RNA binding protein (circZFR) serves as a crucial regulator in many human cancers." (PMID 32831653, 2020). "As for circRNA zinc finger RNA binding protein (circZFR, hsa_circ_0072088), it has been identified as an oncogenic modulator in many human cancers, such as renal carcinoma, bladder cancer and non-small cell lung cancer." (PMID 32831653, 2020). "Zinc finger RNA binding protein (ZFR) is involved in the regulation of growth and cancer development." (PMID 27177590, 2016). "The role of ZFR and ZNF565 in cellular proliferation and survival, especially in cancer and in the context of PI3K pathway inhibition, are not yet known." (PMID 28561737, 2017).
infection (1 paper, 2018). The state of being infected such as from the introduction of a foreign agent such as serum, vaccine, antigenic substance or organism. "Together, these alternative splicing events represent several additional pathways by which ZFR can modulate the response to infection." (PMID 29559679, 2018). "Together, our data suggest that regulation of ZFR in macrophage differentiation guards against aberrant interferon responses and reveal a network of mRNA processing and decay that shapes the transcriptional response to infection." (PMID 29559679, 2018). "Genes upregulated by ZFR depletion included many well-characterized ISGs, suggesting that ZFR suppresses basal type I interferon signaling in the absence of infection." (PMID 29559679, 2018). "We show here that ZFR is the linchpin of a mechanism that controls RNA processing and decay to strongly affect the magnitude of IFNB1 transcriptional induction in response to infection." (PMID 29559679, 2018).
neurological disorder (1 paper, 2018). "The highly conserved zinc finger RNA-binding protein (ZFR) is essential for mouse early embryonic development and mutated in the human neurological disorder hereditary spastic paraplegia, but its physiological and biochemical functions are mostly unknown." (PMID 29559679, 2018).
ZFR also shares sentences with these, for which no sentence is quoted: gastric cancer (3 papers); colorectal cancer (2); gastric tumors (1); glioma (1); myeloid malignancies (1); papillary thyroid cancer (1); Thyroid Carcinoma (1).